EZH2 (enhancer of zeste 2 polycomb repressive complex 2 subunit)
Diseases named in the same sentence as EZH2 in open-access papers (continued):
Sharing a sentence is not in itself a finding about the gene and the disease.
cancer (continued). "A recent study indicated that the genomic loss of miR-101 leads to Ezh2 overexpression in human cancer samples, suggesting the physiological significance of miR-101-regulated Ezh2 function in PCa development." (PMID 20478051, 2010). "In particular, Polycomb protein EZH2 (Enhancer of Zeste 2) is a histone methyltransferase that is often overexpressed in human cancers and is associated with cancer aggressiveness." (PMID 19340297, 2009). "Here, we report that the nuclear respiratory factor 1 gene (NRF1) is the gene whose expression is most strongly correlated with that of the EZH2 gene in various cancer cell lines and that changes in NRF1 expression consistently cause changes in EZH2 expression in cancer cells." (PMID 42140904, 2026). "EZH2, a histone methyltransferase, has been shown to trigger genomic instability and activate oncogenic signaling in breast tumor-initiating cells, a subset of cancer stem cells implicated in breast cancer progression." (PMID 39982247, 2025). "Moreover, DZNep treatment has selectively eliminated BRCA1-mutated cells by modifying EZH2 transcription, a crucial factor in DNA repair and cancer cell proliferation." (PMID 40136510, 2025). "EZH2 is relevant in normal processes such as cellular differentiation and development, but its deregulation has been associated with multiple hallmarks of cancer, such as stemness, proliferation, apoptosis and drug resistance." (PMID 41153744, 2025). "Moreover, cisplatin resistance has been linked to EZH2 overexpression in different cancers including cervical, ovarian, and breast." (PMID 41614754, 2025). "Notably, few of these mutations have also been detected as somatically acquired mutations in cancers (e.g., EZH2 NM_004456: p.D664V, p.R684C and p.Y733*), and consistently, tumors, such as neuroblastoma, have been detected in some WVS patients." (PMID 41153408, 2025). "EZH2, a histone methyltransferase and key epigenetic regulator, has been extensively linked to cancer progression through its role in transcriptional repression of tumor suppressor genes and promotion of cancer stem cell-like properties." (PMID 40584614, 2025). "Moreover, overexpression of PRC2 core components, especially of the catalytic subunit EZH2, is observed in different types of cancers and is associated with poor prognosis." (PMID 40678543, 2025). "Additionally, increased EZH2 levels are associated with reduced sensitivity to chemotherapy in diverse cancer types." (PMID 38785979, 2024). "EZH2 mutations and abnormal expression have been implicated in the onset and progression of cancer." (PMID 39769907, 2024). "Thus, telomere dysfunction induces enhancer of zeste homolog 2 (EZH2) repression by APC-deficient cancer stem cells, resulting in the derepression of WNT antagonists, hence triggering the differentiation of the neighboring normal stem cells." (PMID 39201522, 2024). "Consequently, inhibiting EZH2 results in loss of chromatin compaction, potentially facilitating drug-DNA interactions, DNA damage, and subsequent cancer cell death." (PMID 38600608, 2024). "In this review, we delve into the epigenetic regulation mediated by EZH2/PRC2 in HNSCC, with a specific focus on exploring the potential roles and mechanisms of EZH2, its crucial contribution to targeted drug therapy, and its association with cancer markers and epithelial–mesenchymal transition." (PMID 38600608, 2024). "ARID1A mutation may be associated with cancer cell sensitivity to EZH2 inhibitor therapy as well as PARP inhibitor drugs due to its role in DNA damage repair." (PMID 38543097, 2024).
cancer (continued). "Aberrant expression of wild-type EZH2 has similarly been implicated in various adult cancers." (PMID 39766049, 2024). "Indeed, SMARCA4-deficient cancer cells showed sensitivity to inhibition of methyltransferase EZH2, the catalytic subunit of PRC2." (PMID 39697230, 2024). "In addition we found that EZH1 p.A678G is equivalent to the cancer-associated EZH2-p.A677G variant, which modifies the substrate preference of EZH2 leading to a change in H3K27me0 to me3 kinetics that results in increased H3K27me3 levels." (PMID 37433783, 2023). "In addition, a more detailed mutational landscape of EZH2 in TCGA pan-cancer samples was explored and depicted through the Sangerbox 3.0 database." (PMID 36545914, 2023). "The EZH2 gene is associated with immune infiltration in HCC cancer and affects the cell cycle." (PMID 37853322, 2023). "Given that EZH2 gene mutations might serve as a promising molecular target for the treatment of various human cancers, the mutational profile of EZH2 in human cancers was investigated using TCGA pan-cancer samples." (PMID 36545914, 2023). "In addition, the effect of EZH2 in malignancy has been documented to be largely associated with glucose metabolism of cancer cells, which is recognized as a hallmark of cancer growth and metastasis." (PMID 37179372, 2023). "EZH2 overexpression is often associated with advanced malignant tumor stages and poor prognosis." (PMID 37924077, 2023). "The major effect of EZH2i works on cancer cells with EZH2-activating mutations." (PMID 36627707, 2023). "Compared with matched normal tissues, EZH2 was aberrantly expressed in most cancers either at the mRNA or protein level, which might be caused by genetic mutations, DNA methylation, and protein phosphorylation." (PMID 36545914, 2023). "The aberrant expression and mutation of p300/CBP and EZH2 has been reported in human cancers." (PMID 37168723, 2023). "This suggests that targeting EZH2 could be a potential therapeutic strategy for ARID1A‐deficient cancers." (PMID 38041544, 2023). "EZH2 is overactive in cancer cells through functionally acquired mutations and overexpression." (PMID 36672374, 2023). "Importantly, higher EZH2 expression was strongly associated with higher cancer progression and worse survival in HCC patients." (PMID 37085881, 2023). "The results of our study give way to future studies with larger sample size to further strengthen the association of EZH2 immunoexpression in cancer cervix patients which may aid in development of the targeted therapy in near future." (PMID 37131568, 2023). "Moreover, EZH2 is frequently overexpressed in many cancer types and is associated with a poor prognosis 19-22." (PMID 35813302, 2022). "In addition, our analysis suggests that EZH2-rich domains promote the transcriptional repression of genes associated with cancer and cellular senescence, promoting disease progression." (PMID 36172073, 2022). "However, let-7c binds to the 3'-UTR of JMJD1A and EZH2 and shifts their expression in a feedback loop, predisposing them to cancer phenotype amelioration." (PMID 35087589, 2022). "The RNAs bound by EZH2/JARID2 were also closely associated with cancer pathways in HepG2 cells." (PMID 36578923, 2022). "EZH2 has been implicated as an important cancer target in different types of cancers." (PMID 35269532, 2022). "The high expression of EZH2 and the decreased expression of p57 can promote the occurrence of small hepatocellular carcinoma, and the deficiency of the P57 gene was related to the low differentiation of cancer cells." (PMID 35321452, 2022). "Interestingly, low EZH2 levels correlate with poor survival in patients with BRCA2-mutated cancers, suggesting that EZH2 expression levels, similarly to PTIP, can serve as a biomarker for patient response to PARPi therapy." (PMID 36568963, 2022). "Aberrant EZH2 expression has been associated with various human cancers." (PMID 35419278, 2022).
cancer (continued). "Moreover, EZH2 expression and cancer stage were identified as the independent risk factors affecting LIHC patients' prognosis." (PMID 35855852, 2022). "Numerous studies have implicated EZH2 in cancer pathophysiology." (PMID 36230683, 2022). "Other alterations in this gene included missense mutations and possible deletions on chromosome X. Since KDM6A loss has been shown to sensitize cancer cells to EZH2 inhibition (for example to FDA-approved tazemetostat) and most of our patients were men, further studies would be desirable." (PMID 35664801, 2022). "For this reason, it would be important to investigate whether EZH2 is regulating gene repression of cancer-associated genes through silencers." (PMID 36172073, 2022). "Whether TASOR might have a role in cell pluripotency, suppression of cell differentiation and, more generally, be linked to cancer progression as demonstrated for EZH2 or other chromatin regulators is an important question for future studies." (PMID 36309692, 2022). "In addition, investigations about the SWI/SNF complexes and polycomb-repressive complexes in cancer have indicated that cancers that harbor SWI/SNF subunits mutations or deletions are sensitive to the inhibition of EZH2." (PMID 36361605, 2022). "The onset or cancer progression may be associated with mutations affecting the catalytic SET-domain of EZH2 that is essential for H3K27 methylation." (PMID 35046519, 2022). "The mutation or overexpression of EZH2 is associated with a variety of cancers." (PMID 35743172, 2022). "EZH2 is amplified and overexpressed and is associated with poor survival in various cancers." (PMID 35085106, 2022). "It has been demonstrated that aberrant activation of NF-κB could be associated with EZH2 overexpression or dysregulation in cancer." (PMID 36430394, 2022). "A different interaction was found between NF-κB and EZH2 in endothelial cells infected with Kaposi sarcoma-associated herpesvirus in which latent viral genes were found to activate NF-κB, promoting inflammatory cascade activation and cancer progression." (PMID 36430394, 2022). "Excellent efficacy of EZH2 inhibitors in cancer is likely to cause the problem of drug resistance." (PMID 34149432, 2021). "Dysregulation of EZH2 as a histone modifier causes the proliferation of cancer cells and promotes their survival and metastasis, resulting in invasion and progression of a malignant tumor." (PMID 35008250, 2021). "Indeed, regression of INI-deficient rhabdoid tumors after EZH2 inhibition was observed based on preclinical evaluation with human cancer cell lines and xenograft models in immunodeficient mice." (PMID 34830753, 2021). "Abnormal EZH2 expression may be implicated in various immune-related diseases, including autoimmune diseases, infection, graft-versus-host disease, and cancer." (PMID 34737746, 2021). "EZH2 is associated with the aggressiveness and advanced progression of several types of cancers." (PMID 34124072, 2021). "Studies have suggested that high levels of EZH2 expression in cancer tissue may be strongly linked to poor patient prognosis." (PMID 32303902, 2021). "In fact, the overexpression of EZH2 has been shown to be associated with invasive growth and poor clinical outcomes in many malignant tumors, including breast, prostate, gastric, endometrial and hematologic cancers, even though the prognostic impact of H3K27me3 expression is variable." (PMID 35186711, 2021). "Besides AKT, a plethora of enzymes have been associated with posttranslational EZH2 phosphorylation at a variety of amino acid residues and in different cancer entities." (PMID 34943970, 2021). "EZH2 expression is associated with increased proliferation of several cancer cell lines." (PMID 33658396, 2021).
cancer (continued). "Overexpression of EZH2 results in the myeloproliferative disorder in mice, and has been shown to be associated with aggressiveness and metastasis of different types of human cancers such as prostate cancer, breast cancer, bladder cancer and melanoma 6-10." (PMID 34093860, 2021). "It is noteworthy, that some of the transcription factors which have been previously linked to EZH2 activation, albeit in other cancer entities, underlie transcriptional control by NFATc1 (MYC, STAT3) or represent well-characterized NFATc1 partner proteins (STAT3, ELK1)." (PMID 34943970, 2021). "However, missense mutations in EZH2 can also exert a cancer-promoting effect in hematological tumors." (PMID 34737746, 2021). "EZH2 mutations or overexpressions are associated with many types of cancer." (PMID 34737746, 2021). "Moreover, cancer stem cells exhibit reduced EZH2 expression that is associated with higher transcriptional activity and cellular plasticity." (PMID 34140011, 2021). "However, the resistance of cancer cells to EZH2 inhibitors and the underlying mechanisms still need to be explored." (PMID 34671029, 2021). "On the other hand, several cancers are associated with EZH2 overexpression." (PMID 34869358, 2021). "In addition, EZH2 is the second histone methyltransferase gene that is found to be mutated in cancer." (PMID 34604069, 2021). "Interestingly, there is interest in developing therapeutic targets in ARID 1 A-mutated cancers, including enhancer of zeste homolog 2 (EZH2)." (PMID 33344089, 2020). "The loss of the pRb-EZH2 complex provokes loss of the H3K27me3 mark at these elements, leading to dispersion or loss of heterochromatin and probably disorganized proliferation as observed in cancer cells." (PMID 32664691, 2020). "In cancer, EZH2 seem to be implicated in cell proliferation and invasion, as well as metastasis." (PMID 32708698, 2020). "Uterine EZH2 expression exerts a critical role in development and function of this organ with deletion of this gene resulting in uterine hyperplasia and expression of cancer-associated transcripts." (PMID 33732505, 2020). "EZH2 alterations have been associated with cancer progression." (PMID 32924329, 2020). "Besides acquisition of gain-of-function mutations, EZH2 is overexpressed in various cancer types and its targeting has been shown to inhibit cell proliferation and metastasis." (PMID 32906688, 2020). "EZH2 is overexpressed in various cancers and is associated with decreased patient survival." (PMID 32635336, 2020). "Mutations and aberrant expression of EZH2 are frequently found in cancer and targeting this methyltransferase may have therapeutic potential in different disease entities." (PMID 33371192, 2020). "Enhancer of zeste homolog 2 (EZH2) is an oncogenic protein implicated in multiple cancer types." (PMID 33046994, 2020). "The expressions of LAT1 and EZH2 have also been linked with more undifferentiated cancer." (PMID 33086625, 2020). "It is interesting to note that EZH2 has been implicated as an oncogene in multiple cancer types, raising the question of whether it can be considered a universal anticancer drug target." (PMID 33050946, 2020). "The gain-of-function role for mutant EZH2 in cancer is always resulted by the other chromatin regulators’ loss-of-function mutations which can normally antagonize EZH2 activity, such as the ubiquitously transcribed tetratricopeptide repeat gene on X chromosome (UTX)." (PMID 33163485, 2020). "Ezh1, in some cases, may compensate for the loss of Ezh2, and can also potentially have a role in cancer." (PMID 33732505, 2020). "Furthermore, clinical investigations have shown that EZH2 is aberrantly upregulated in various malignant tumors such as prostate and breast cancer and is associated with advanced stages and poor prognosis." (PMID 33180829, 2020). "Furthermore, there was a significantly higher EZH2 mRNA expression in cancers with confirmed BRCA1 mutations (P = 0.013)." (PMID 33230143, 2020).
cancer (continued). "Reports of EZH2 mutations in cancer have increased in recent years." (PMID 30984620, 2019). "Additionally, in a previous report, the mechanism underlying the upregulation of WHSC1 was induced by EZH2 through suppression of a set of miRNAs that lead to the transcriptional repression of WHSC1 in cancer cells." (PMID 31092221, 2019). "In summary, our results suggest that, once EZH2 is aberrantly upregulated or activated in normal somatic cells due to gain of function mutations or amplifications, a series of cancer-promoting proteins will be abnormally maintained or upregulated, forming a network promoting tumorigenesis." (PMID 31130994, 2019). "EZH2 may also have suppressive roles as inactivating mutations are found in some cancers, e.g., T-cell acute lymphoblastic leukemia." (PMID 30823421, 2019). "Taken together, these discoveries demonstrate how EZH2 gain- or loss-of-function mutations can promote the progression of cancer in a context-specific fashion, through increasing or decreasing H3K27 trimethylation levels, which in turn regulate specific patterns of gene expression." (PMID 31097014, 2019). "Identifying mechanisms underlying EZH2 overexpression in cancer, such as those described here, may allow selective targeting of aberrant PRC2 activity while minimizing toxicity in normal tissues." (PMID 31263101, 2019). "Thus, this represents a novel strategy to overcome and/or prevent the development of de novo resistance to EZH2 inhibitors in ARID1A-mutated cancers." (PMID 30297712, 2018). "The genomic loss of miR-101 led to overexpression of EZH2, resulting in cancer progression." (PMID 29921304, 2018). "The expression of LAT1 and EZH2 were also linked with more undifferentiated cancer." (PMID 30103560, 2018). "Following the discovery that EZH2 functions as a chromatin modifying enzyme, a large number of reports have linked EZH2 to hallmarks of cancer via modulating the epigenome, leading to aberrant transcriptome in cancer cells making it a promising target for therapy." (PMID 30761216, 2018). "Mutation or overexpression of EZH2 has been linked to many forms of cancer." (PMID 30486864, 2018). "The mechanism of resistance to EZH2 inhibitors in cancers with inactivating SWI/SNF mutations is unknown." (PMID 30297712, 2018). "It is possible that EZH2-mutated or -overexpressed cancer cells may show higher sensitivity to the mTOR inhibitors." (PMID 28717873, 2018). "Therefore, our data are in line with what was already reported for other solid tumours and highlight in the TME of MpM an association between the loss of Th1-specific features and EZH2 expression in cancer cells." (PMID 30510965, 2018). "The authors also showed that loss of EZH2 methyltransferase activity down-regulated the Wnt/β-catenin signalling pathway, which is known for its role in the stemness of cancer stem cells, via upregulation of CXXC4, NKD1 and PRICKLE1 with subsequent inhibition of DVL protein." (PMID 30555699, 2018). "Importantly, previous work revealed a functionally antagonistic relationship between SWI/SNF and PRC2 complexes, resulting in a proposed dependency of SWI/SNF-mutated carcinomas on EZH2, a histone methyltransferase subunit of the PRC2 complex." (PMID 30138427, 2018). "Mutations of EZH2 have been identified in many cancer types." (PMID 28561778, 2017). "In addition, EZH2 is also strongly linked with the maintenance of cell identity, cell cycle regulation, and particularly cancer biology being currently at the cutting edge of the research." (PMID 29156711, 2017). "Moreover, the candidate cancer driver mutations in Ezh2 and Hras were highly enriched in X10 and IGF1 tumors." (PMID 28173837, 2017).